S100A4 (S100 calcium binding protein A4)
Diseases named in the same sentence as S100A4 in open-access papers (continued):
Sharing a sentence is not in itself a finding about the gene and the disease.
colon carcinoma (continued). "IFN-γ-downregulation of S100A4 is also observed in OS, breast, and colon carcinoma cells, which was increased by the inhibition of S100A4 transcription, but not caused by the IFN-γ-mediated decrease in S100A4 mRNA stability." (PMID 29069865, 2017). "S100A4‐negative stage III colon cancer patients had an estimated 3‐year relapse‐free survival of 66% and 55% in cohorts 1 and 2, respectively, implying that these patients likely would benefit from additional treatment." (PMID 27273130, 2016). "Our results are broadly consistent with those obtained previously where a similar increase in immunocytochemically-detected S100A4 was observed in malignant relative to non-malignant colonic tumour specimens." (PMID 11875708, 2002). "Furthermore, the U.S. Food and Drug Administration (FDA)-approved anthelmintic drug niclosamide was identified to inhibit S100A4-induced metastasis formation of colon cancer, by preventing β-catenin/T-cell factor (TCF) complex formation and therefore transcription of S100A4." (PMID 32722137, 2020). "After being activated by the extracellular S100A4 protein binding, RAGE activates the mitogen-activated protein kinase (MAPK)/extracellular signal-regulated kinase (ERK) and NF-κB signaling pathways, augmenting the potency for tumor growth, cell migration, and invasion in colon cancer." (PMID 30111999, 2018). "However, in situ hybridization revealed that in some other specimens of colon carcinoma which were positive in the quantitative RT–PCR assay, S100A4 mRNA appeared not to be generally present in the carcinoma cells." (PMID 11875708, 2002). "Altogether, unlike MC38 S.C. colon tumors, only peri-tumor myofibroblasts decreased in Pan02 S.C. tumors in the TME of the S100a4-Cre; Ext1f/f mice compared to the control mice." (PMID 36809261, 2023).
melanoma (43 papers, 2009 to 2025). A malignant, usually aggressive tumor composed of atypical, neoplastic melanocytes. "Overexpression of S100A4 was also associated with RAGE upregulation, indicating a role for S100A4/RAGE signaling in metastatic activation of melanoma." (PMID 37190188, 2023). "In this study an association of elevated extracellular S100A4 and a prometastatic phenotype in melanoma cells could be demonstrated." (PMID 26928771, 2016). "S100A4 and ITGAV displayed dataset-specific patterns: negatively associated with SC and CP in metastatic melanomas, but positively with MHC and EC in primary ones." (PMID 40943183, 2025). "Tumor cells actively secrete S100A4 via an endoplasmic reticulum–Golgi-dependent mechanism, enhancing melanoma’s metastatic potential." (PMID 39769332, 2024). "In contrast, S100A4 (Metastasin) and S100A13 are implicated in promoting tumor cell survival and metastasis in cancers, including melanoma." (PMID 39769332, 2024). "For example, S-100A1, S-100A2, and S-100A4 are produced by melanocytes, and have been found to be elevated in some cases of melanoma." (PMID 37504268, 2023). "In melanoma cells, the interaction of extracellular S100A4 with RAGE induced pre-metastatic events, such as increased migration, invasion, and reduced adhesion." (PMID 36982351, 2023). "The results of these studies strongly suggest that the S100A4/RAGE axis is an important contributor to metastasis in melanoma tumors." (PMID 33256110, 2020). "As previously discussed, S100A4 is involved in the metastatic processes in other cancer types, and similar observations were made in melanoma." (PMID 32722137, 2020). "sRAGE was shown to reduce motility and pro-metastatic stimulation of A-375 melanoma cells by stopping S100A4-RAGE signaling axis." (PMID 30836666, 2019). "The increase in S100A4 expression, together with reduced E-cadherin expression results in the metastatic potential of human malignant melanoma." (PMID 29069865, 2017). "In addition, S100A4 expression has been associated with the prognosis of several other tumor types including ovarian, liver, prostatic, pancreatic, bladder, lung, esophageal, gallbladder, and gastric cancers as well as in osteosarcoma, leukemia, malignant melanoma, and brain tumors." (PMID 29069865, 2017). "High extracellular S100A4 level is a specific characteristic of malignant melanoma cells for the mediation of pro-metastatic endothelial dysfunction and for the promotion of metastasis via interaction with RAGE in a paracrine manner." (PMID 29069865, 2017). "For this purpose, the highly metastatic A375 melanoma cell line was chosen as a model because of its comparably high baseline expression and synthesis of S100A4." (PMID 26928771, 2016). "S100A4 secretion in wild‐type melanoma cells and transgenic A375 cells was demonstrated showing highest amounts of S100A4 concentration in A375‐hS100A4 cells." (PMID 26928771, 2016). "The observation of a classical, BFA‐sensitive, ER–Golgi pathway‐dependent secretion of S100A4 in melanoma cells, first of all, contributes to further understanding of the enormous cell‐ and protein‐specific metabolic heterogeneity of the S100 family." (PMID 26928771, 2016). "S100A4, a member of the S100 protein family of EF‐hand calcium‐binding proteins, is overexpressed in various tumour entities, including melanoma, and plays an important role in tumour progression." (PMID 26928771, 2016). "S100A4 overexpression in M21 melanoma cells simulates tumor vascularization in human melanoma xenograft models in addition to inducing transmigration." (PMID 27598148, 2016). "In consequence, we suggested that interaction of extracellular S100A4 with RAGE contributes to prometastatic activation of melanoma." (PMID 26928771, 2016).
melanoma (continued). "Paracrine-mediated signaling of S100A4 secreted from melanoma cells with its cognate receptor, receptor for advanced glycation end-products (RAGE), on endothelial cells enabled transmigration." (PMID 27598148, 2016). "Among the upregulated genes was S100A4, a member of the S100 protein family of proteins that serve as markers for human melanoma." (PMID 25642713, 2015). "S100A4 has been demonstrated as protein regulating tumor growth and angiogenesis in melanoma xenograft model and S100A4 has shown increased expression in invasive melanoma cell lines." (PMID 24733089, 2014). "For this, we immunostained the microvessels in tumor tissues formed by B16-BL6 melanoma cells that express little S100A4 with anti-CD31 and anti-S100A4 antibody." (PMID 23929008, 2014). "In vivo overexpression of S100A4 led to a significant increase in tumor growth and vascularization in a human melanoma xenograft M21 model." (PMID 24023743, 2013). "Closer characterization of S100A4+ cells in primary tumors showed that there were indeed delaminating melanoma cells expressing HMB45 and MART-1 antigens and exhibiting a fusiform morphology (white arrows)." (PMID 21980263, 2011). "The number of S100A4+ cells expressing melanoma differentiation antigens was reduced in tumors depleted from PMN-MDSC." (PMID 21980263, 2011). "Another RAGE ligand, S100A4, is highly overexpressed in the melanoma microenvironment." (PMID 39769332, 2024). "In addition, S100A4 functions as a paracrine mediator of melanoma BM by interacting with endothelial RAGE." (PMID 37190188, 2023). "Furthermore, in vivo experiments have shown that mice injected with melanoma cells and expressing S100A4 or RAGE lead to the formation of brain metastases." (PMID 37190188, 2023). "Melanoma cell lines express S100A4 in the extracellular region." (PMID 37190188, 2023). "S100A4 stimulation was also connected with metabolic reprogramming in melanoma." (PMID 36982351, 2023). "In a mouse model of melanoma, silencing of S100A4 by siRNA reduced tumor growth and angiogenesis." (PMID 34209679, 2021). "In summary, S100A4 induces metastatic signalling and promotes cell migration in malignant melanoma." (PMID 32722137, 2020). "The increased S100A4 expression might also be because the plasma treatment killed many of the melanoma cells." (PMID 32917026, 2020). "S100A4 expression has been demonstrated in several malignancies such as malignancies of the pancreas, stomach, breasts, ovaries, kidneys, lungs, liver, prostate, and bones, in tumors of the urinary bladder, and in melanomas." (PMID 30111999, 2018). "A neutralizing monoclonal antibody targeting S100A4, 5C3, has been shown to prevent endothelial cell migration of melanoma cells in an immunodeficient mouse xenograft model, thus additional research on the clinically relevant efficacy of targeting S100A4 should be explored." (PMID 27598148, 2016). "In wild‐type melanoma cells, S100A4 secretion correlates well with S100A4 expression/synthesis." (PMID 26928771, 2016). "However, the activity of extracellular S100A4 within the metastatic cascade, and the participation of S100A4 in malignant melanoma are still not fully understood." (PMID 26928771, 2016). "Therefore, the present study aimed at a detailed discrimination of S100A4 secretion pathways in the human melanoma cell line A375 as model." (PMID 26928771, 2016). "Interestingly, expression of S100A4 correlates with shorter patient survival in several cancers, including melanoma." (PMID 21980263, 2011). "We measured the number of S100A4+ melanoma cells in primary tumors." (PMID 21980263, 2011).
melanoma (continued). "In transdifferentiated A375 cells the melanoma markers MKI67, MITF, S100A4, S100A10, MMP2 and MMP9 were significantly downregulated." (PMID 40715046, 2025). "The paracrine secretion of S100A4 is believed to induce RAGE-dependent endothelial dysfunction, facilitating melanoma cell migration." (PMID 39769332, 2024). "S100 subtypes: S100B, S100P, S100A4, S100A6, and S100A13 are often found in melanoma, with S100P being positive in all melanoma subtypes." (PMID 37504268, 2023). "S100A4 is a ligand of RAGE and has been shown to stimulate metastasis in various cancer models, including melanoma, through its interaction with RAGE." (PMID 33256110, 2020). "Once MDSCs were depleted, the expression of S100A4 and Vimentin which downregulated the expression of E-cadherin and promoted EMT would be decreased in a murine melanoma model." (PMID 32092078, 2020). "Another study found that the overexpression of preferentially expressed antigen of melanoma (PRAME) induces the repression of three genes: Hsp27, S100A4 and p21." (PMID 28903396, 2017). "In conclusion, active secretion of S100A4 and its subsequent interaction with coexpressed RAGE in an autocrine manner is suggested to be an important prometastatic attribute in those melanoma cases characterized by a high secretion rate of S100A4." (PMID 26928771, 2016). "Expression of S100A4 and RAGE was investigated in three different human melanoma cell lines (A375, A2058, and MEL‐JUSO) well‐established in many laboratories." (PMID 26928771, 2016). "However, exact mechanisms how S100A4 stimulates metastasis in melanoma are still unknown." (PMID 26928771, 2016). "S100A4 levels are lower in metastatic melanoma compared with primary tumors, while S100A7, S100A8, and S100A9 levels appear to be higher in malignant melanoma compared with normal melanocytes." (PMID 19859558, 2010). "Indeed, in the context of melanoma xenograft tumors, we showed that overexpression of RAGE resulted in the upregulation of S100A2, S100A4, S100A6, and S100A10, both at the transcript and protein levels." (PMID 37627239, 2023). "Metastatic melanoma cells revealed a large increase in the expression of S100A4 following plasma treatment, and non-metastatic melanoma cells showed an increase to a minor extent." (PMID 32917026, 2020). "A recent study also suggested that S100A1 competes with S100A4 for binding to the V-domain of RAGE, suggesting that S100A1/RAGE interaction might influence cell proliferation in melanoma." (PMID 33256110, 2020). "S100A4 secreted by tumor and stromal cells can stimulate angiogenesis by synergizing with VEGF to promote endothelial cell migration through the increase in RAGE-induced KDR and MMP-9 expression in a melanoma animal xenograft-model." (PMID 29069865, 2017). "This has been also intensively discussed for melanoma, however, the functional importance of extracellular S100A4 has not been clearly established in this cancer." (PMID 26928771, 2016). "However, data on the interaction of extracellular S100A4 with RAGE and its influence on the metastatic capacity of human melanoma cells are scarce." (PMID 26928771, 2016). "S100A4 not only activates the nuclear factor‐kappa B (NF‐κB) pathway and leads to the release of the tumor necrosis factor (TNF)‐α, but also shapes an inflamed TME by inducing the secretion of IL‐8 and C—C chemokine ligand 2 (CCL2), playing an oncogenic role in malignant melanoma." (PMID 37414584, 2023).
melanoma (continued). "The microarray results indicated that microenvironmental cues can trigger switching of melanoma cells to a neural stem cell-like pattern, as six genes related to neural stem cell and neural stem cell niche biology were upregulated: SOX2, ID4, GFRA2, S100A4, LGI4, and GJB1." (PMID 25642713, 2015). "To address the question of whether S100A4 could serve as a therapeutic target in vivo, we evaluated the effect of S100A4 overexpression in a non-expressing human melanoma cell line (M21)." (PMID 24023743, 2013). "In addition, copper-mediated oxidation of the cysteine residues in the cross-linking of S100A4 prometastatic activity in tumor microenvironment results in an increase in NF-κB activation and TNF-α secretion in human melanoma cells, particularly in RAGE-transfected melanoma cells." (PMID 29069865, 2017).
gastric cancer (35 papers, 2002 to 2025). A primary or metastatic malignant neoplasm involving the stomach. "It seems likely that MACC1 and S100A4 also cooperate in other cancer entities, as the two biomarkers were described for improved prognosis of ovarian or gastric cancer, which underlines its considerable cross-entity potential." (PMID 36008464, 2022). "S100A4 overexpression in the poorly differentiated gastric cancer is associated with positive lymph node involvement and peritoneal tumor dissemination." (PMID 29069865, 2017). "Furthermore, we have confirmed the diagnostic and prognostic value of S100A4 transcripts in plasma of patients with CRC or gastric cancer, particularly by combined assessment, together with MACC1 transcripts." (PMID 30927479, 2019). "Growth, signaling, differentiation, and motility are susceptible to changes in S100A4 expression and the knock-down of S100A4 by RNA interference has been reported to inhibit cell growth and motility of various cancer cell lines like gastric cancer or osteosarcoma." (PMID 22878175, 2012). "S100A4 gene overexpression has been related to the malignant potential of some tumors and has been closely associated with metastasis in several human cancers, including colorectal, breast, ovary, thyroid, pancreatic, lung, esophageal, prostate and gastric cancer." (PMID 20515499, 2010). "This suggests that the expression level of S100A4 affects the regulatory effect of OSTM1 on the invasive ability of gastric-cancer cells." (PMID 39852172, 2025). "This study aims to investigate how OSTM1 promotes gastric-cancer proliferation and metastasis by enhancing the S100A4 signaling pathway." (PMID 39852172, 2025). "The results demonstrate that high expression of OSTM1 in gastric-cancer tissues is significantly associated with the invasiveness and metastatic potential of gastric cancer, and this effect may be mediated through the regulation of the S100A4 signaling pathway." (PMID 39852172, 2025). "Immunohistochemical staining results also show that S100A4 is highly expressed in gastric-cancer tumor tissues." (PMID 39852172, 2025). "We analyze the expression and correlation of OSTM1 and S100A4 in gastric-cancer tissues through clinical samples and explore the regulatory effects of OSTM1 on S100A4 expression using in vitro cell experiments and in vivo animal models." (PMID 39852172, 2025). "A recent study found that S100A4 can promote the invasion and metastasis of gastric-cancer cells by upregulating the expression of MMP9." (PMID 39852172, 2025). "This suggests that S100A4 mediates the chemotactic effect of OSTM1-overexpressing gastric-cancer cells on fibroblasts." (PMID 39852172, 2025). "In this study, we investigated the role of OSTM1 in gastric-cancer proliferation and metastasis through the enhancement of the S100A4 signaling pathway." (PMID 39852172, 2025). "In conclusion, S100A4 is a key molecule for OSTM1 to exert its promoting effect on gastric-cancer invasion and metastasis." (PMID 39852172, 2025). "Particularly, how OSTM1 influences gastric-cancer cell proliferation and metastasis through the regulation of the S100A4 signaling pathway has rarely been reported in the literature." (PMID 39852172, 2025). "The ridgeline plot results show that OSTM1 and S100A4 have a co-expression trend in the gastric-cancer data analysis." (PMID 39852172, 2025). "According to the analysis of the KM Plotter database, gastric-cancer patients with high S100A4 mRNA expression have shorter overall survival (OS)." (PMID 39852172, 2025). "In summary, our study reveals the key role of OSTM1 in promoting gastric-cancer proliferation and metastasis by enhancing the S100A4 signaling pathway, providing new insights for molecular targeted therapy of gastric cancer." (PMID 39852172, 2025). "OSTM1 promotes gastric-cancer progression by upregulating S100A4 and modifying the tumor microenvironment through enhanced angiogenesis and fibroblast activation." (PMID 39852172, 2025).